TNF (tumor necrosis factor)
Diseases named in the same sentence as TNF in open-access papers (continued):
Sharing a sentence is not in itself a finding about the gene and the disease.
COVID-19 (continued). "When comparing the frequency of patients with elevated levels of IL-10, IL-6, and TNF-α and their combinations or overlaps, we found a significant difference (p < 0.001) between the non-, moderate, severe, and critical COVID-19 groups." (PMID 40508859, 2025). "Among all cytokines released in the COVID-19 cytokine storm, interleukin 1 (IL-1), interleukin 6 (IL-6), TNF-α and IFN-γ are prominent." (PMID 40397955, 2025). "We enrolled 150 COVID-19 patients, who were classified by their systemic TNF and IFN-γ levels (high (H) or normal–low (N-L)) as TNFHIFNγH, TNFHIFNγN-L, TNFN-LIFNγH, and TNFN-LIFNγN-L." (PMID 39940907, 2025). "COVID-19 can activate the NF-κ B pathway by generating ROS, leading to the release of inflammatory cytokines (IL-1, IL-6, and TNF-α)." (PMID 41156098, 2025). "Based on these findings, we determined that anti-TNF-α antibody therapy would be appropriate for managing COVID-19-induced UC relapse." (PMID 40024991, 2025). "TNF-α concentrations were lower in critical COVID-19 patients compared to those in moderate and severe COVID-19 patients." (PMID 40508859, 2025). "Associations between severe COVID-19 and elevated levels of pro-inflammatory cytokines like IFN-γ, TNF-α, and IL-17 and anti-inflammatory cytokines including IL-6 and IL-10, have been reported." (PMID 40934185, 2025). "Cytokine levels are a crucial factor in the renal pathology of COVID-19 patients, compared to other viral infections, resulting in elevated levels of cytokines such as IL-1β, IL-6, IL-18, and TNF-α." (PMID 40863220, 2025). "COVID-19 is characterized by a systemic inflammatory response with elevated cytokines, including IL-6, IL-1β, TNF-α, and interferon-γ." (PMID 41446486, 2025). "SNPs in the TNF-α, IL-6, IL-8, IL-10, CCL5 and CXCL6 genes have been associated with COVID-19 outcomes and with serum cytokine and chemokine levels." (PMID 40881695, 2025). "The platform of hiPSC-CMs has been used as an in vitro SARS-CoV-2 infection model to determine the inflammatory process involved in the ability of TNF-α to exacerbate the cytokine storm and aggravate myocardial damage in patients with COVID-19." (PMID 40697650, 2025). "This systematic review and meta-analysis evaluates the effectiveness, efficacy, and safety of TNF-α inhibitors in the management of COVID-19." (PMID 40481519, 2025). "Comparative analyses of tissue samples from COVID-19 patients and control groups have demonstrated significantly elevated TNF-α expression, suggesting that this signaling pathway is a key driver of angiogenic responses in individuals infected by SARS-CoV-2." (PMID 40362439, 2025). "Our results identify IL-6 and TNF as critical therapeutic targets against COVID-19 in SLE patients, whereas IL-10 relates closely to severe outcomes." (PMID 40643149, 2025). "Cytokine storms, characterized by an excessive release of IL-6, IL-1β, and TNF-alpha, remain a central determinant of disease severity in COVID-19." (PMID 40497938, 2025). "COVID-19 severity is linked to elevated levels of inflammatory mediators, including cytokines (e.g., IL-2, IL-7, IL-10, IFN-γ, and TNF-α) and chemokines (e.g., G-CSF, MCP1, MIP1α, and CXCL10), as well as markers like C-reactive protein, ferritin, and D-dimers." (PMID 40649865, 2025). "In the context of published NNT-s for survival in severe or critical COVID-19, our findings suggest a relatively high efficacy of TNF-α inhibitors in preventing COVID-19-related death." (PMID 40481519, 2025). "These inflammatory cytokines can participate in cytokine storms, leading to liver damage in COVID-19 patients.These inflammatory cytokines, such as TNF-α, can in turn activate NF-κ B, forming a vicious cycle." (PMID 41156098, 2025). "In total, 5 studies reported CRP levels, allowing for the assessment of the biological effect of TNF-α inhibitors in COVID-19." (PMID 40481519, 2025).
COVID-19 (continued). "This aligns with prior work demonstrating that IL-6 overexpression - alongside TNF-α and IL-1β - correlates with severe-stage monocyte activation in COVID-19, though its independent predictive value was attenuated in comprehensive models." (PMID 41184328, 2025). "In the pathophysiology of COVID-19, the initial viral replication phase is typically followed by a robust inflammatory cascade, in which tumour necrosis factor-alpha (TNF-α) plays a central role." (PMID 40481519, 2025). "Elevated serum levels of inflammatory cytokines, such as TNF-α, have been observed in critically ill COVID-19 patients." (PMID 39874384, 2025). "For example, SREBP2 activation is elevated in monocytes from COVID-19 patients, and its inhibitor, Fatostatin, suppresses the expression of pro-inflammatory cytokines such as TNF-α, IL-1β, and IL-6." (PMID 41134862, 2025). "For example, the rs1800629 and rs1800795 variations of proinflammatory cytokines significantly influence the clinical outcomes and systemic inflammatory profiles of COVID-19, elevating TNF-α and IL-6 levels, respectively." (PMID 40438117, 2025). "Supervised machine learning algorithm (RF) was used to predict the COVID-19 severity and chronicity based on immune subset profiling and a 14-plex cytokine panel (TNF-a, IL-4, IL-13, IL-2, GM-CSF, sCD40L, CCL5, CCL3, IL-6, IL-10, IFN-g, VEGF, IL-8, and CCL4." (PMID 40657638, 2025). "But several researches showed that anti-TNF-α treatment has attenuated response to vaccination against COVID-19." (PMID 39850808, 2025). "The primary objective of this study was to investigate the correlation between genetic variations in IL1B, IL6, TNF, and critical outcomes of COVID-19." (PMID 40506975, 2025). "Given the central role of the inflammatory cascade in COVID-19 pathogenesis, there is growing interest in the potential use of tumour necrosis factor-alpha (TNF-α) inhibitors as a therapeutic strategy to mitigate this response and improve patient outcomes." (PMID 40481519, 2025). "Moderate and severe COVID-19 patients showed the highest percentage of overlap with high levels of IL-10 and IL-6 and TNF-α (47 % and 58%, respectively)." (PMID 40508859, 2025). "Studies have shown that circulating levels of IL-6, TNF-α, and IL-1β are significantly elevated in COVID-19 patients with severe disease." (PMID 40806851, 2025). "A previous retrospective study showed that COVID-19 patients exhibit different degrees of elevated levels of inflammatory factors, including IL-1β, IL-2, IL-6, IL-7, IL-8, and TNF-α." (PMID 40438117, 2025). "Increasing histone acetylation in genes regulating pro-inflammatory cytokines like TNF-α and IL-6 was reported in a group of severe COVID-19 patients." (PMID 40002898, 2025). "COVID-19 patient cerebrospinal fluid (CSF) sample presented neuroinflammatory profiles of elevated levels of IL-1β, TNF-α, IL-8, and IL-649,50." (PMID 40760135, 2025). "One such example is pomalidomide, which is known as an angiogenesis inhibitor and tumor necrosis factor production, and has recently gained attention as a repurposable drug to use against COVID-19." (PMID 40997149, 2025). "IL-33 activation has been reported in advanced COVID-19, contributing to severe lung inflammation by activating several proinflammatory cytokines such as IL-6 and TNF-α through the MyD88-MAPK-NF-kB signaling axis." (PMID 40242753, 2025). "The proinflammatory cytokines IL-6 and IL-10 were significantly increased in COVID-19 patients compared to non-COVID-19 patients (p < 0.005), while TNF-α levels were lower in critically ill patients with COVID-19 pneumonia." (PMID 40508859, 2025). "Similar patterns have been observed in COVID-19 patients, where elevated levels of IL-4, IL-10, and TNF-α were detected in serum samples." (PMID 41316426, 2025). "This allows NF-κB to enter the nucleus and trigger the production of pro-inflammatory cytokines such as IL-6, IL-1β, and TNF-α, which are notably elevated in patients with severe COVID-19." (PMID 40219044, 2025).
COVID-19 (continued). "Among the 19 intersecting targets identified between G. pentaphyllum compounds and COVID-19-associated genes, several key nodes—IL1B, IL6, TNF, ACE, and REN—emerged as central in both the protein–protein interaction and compound–target networks." (PMID 41471341, 2025). "TNF-α, a central mediator of cytokine storm and acute cardiac injury, has been widely studied in COVID-19 pathophysiology." (PMID 41472298, 2025). "Several studies have shown that anti-TNF-treated patients with IBD have impaired systemic IgG responses to COVID-19 vaccination." (PMID 40733735, 2025). "Among patients with COVID-19 receiving Empagliflozin, a significant correlation was observed between IL-1, TNF-alpha, IL-6, and blood glucose levels." (PMID 40134446, 2025). "All COVID-19 patient groups presented significantly higher concentrations of inflammatory cytokines, such as s-TNF-α, s-IL-1β and s-IL-6, compared to controls." (PMID 39862311, 2025). "Functionally, we demonstrate that this EAS1-mediated suppression of ACE2 exacerbates cellular apoptosis induced by TNF-α and hypoxia, two key pathological features of severe COVID-19." (PMID 41093073, 2025). "It is important to note that we measured TNF-α levels at admission, and then at day 5 and day 10, and they showed an increase at day 10 in critical COVID-19 patients." (PMID 40508859, 2025). "TRMs from COVID-19 lungs have been reported to exhibit altered chromatin landscapes, including reduced H3K4me3 at loci encoding IFN-γ and TNF, which correlate with T cell exhaustion and reduced effector functions." (PMID 40969755, 2025). "A study indicated that the inflammatory profile (CRP, IL-10, IL-17, IL-6, TNFα, and IL-1β) observed during the acute phase of severe COVID-19 predicts future long COVID symptoms." (PMID 40048451, 2025). "Pro-inflammatory cytokines, such as IL-6, IL-1β, and TNF-α, are known to induce F3 gene expression in both immune and non-immune cells, potentially contributing to the thromboembolic events observed in COVID-19 patients, particularly in severe cases." (PMID 41583455, 2025). "Recent studies have established that immune dysregulation in severe COVID-19 cases is driven by the excessive production of IL-6 and TNF-α, leading to a hyperinflammatory state known as the cytokine storm." (PMID 40137715, 2025). "In light of our findings, further research is warranted to clarify the role of TNF-α inhibitors in COVID-19 treatment." (PMID 40481519, 2025). "In COVID-19, immune effector cells secrete high levels of chemokines and proinflammatory cytokines (e.g., TGFβ, TNFα, IL-33, IL-18, IL-12, IFNγ, IL-6, IL-1β, and IFN-α) in response to SARS-CoV-2 infection." (PMID 40002929, 2025). "COVID-19 is characterized by a dysregulated immune response, leading to the excessive release of pro-inflammatory cytokines such as IL-1β, IL-6, and TNF-α, which contribute to tissue injury and multiorgan dysfunction." (PMID 40710798, 2025). "Overall, these results suggest that CALCA, TNF, and PLAT are strongly associated with COVID-19, while PPARG has a relatively weaker association." (PMID 40766923, 2025). "TNF-α has also been shown to be involved in vascular dysfunction with a pro-thrombotic tendency and cardiovascular illness in post-COVID-19 individuals." (PMID 40137715, 2025). "It is important recognizing CTCL as a possible, although rare, adverse effect of certain drugs and vaccines, and taking a history of vaccinations, especially COVID-19 vaccines, and immunosuppressive drugs such as fingolimod, TNF-a inhibitors, and methotrexate." (PMID 40226161, 2025). "CLAD Exhausted.T cells showed maximal allograft rejection and interferon responses, whereas COVID-19 cells exhibited oxidative phosphorylation and TNF-α activation." (PMID 41122970, 2025).
COVID-19 (continued). "According to our results, it is reasonable to assume that the induction of EndMT in COVID-19 is also ascribable to the presence of several cytokines secreted by macrophages in CM_S1 medium, including IL-1β, IL-6, TNFα, and IFNγ." (PMID 40943589, 2025). "The inflammatory and immune responses triggered by COVID-19 involve various cytokines and immune cells, including but not limited to interleukin (IL)-6, tumor necrosis factor-alpha (TNF-α), IL-1β, IL-8, IL-10, IL-12, IL-17, IL-23, and interferon-gamma (IFN-γ)." (PMID 39886482, 2025). "The levels of pro-inflammatory cytokines IL-6 and TNF-α, which are key indicators of COVID-19 severity, were quantified in serum and lung tissue at 6/7 dpi." (PMID 40868984, 2025). "Systemic inflammation in COVID-19 triggers the release of pro-inflammatory cytokines (IL-6, TNF-α, IL-1β), impairing cardiac function directly and by promoting inflammatory cell infiltration." (PMID 40142859, 2025). "High levels of proinflammatory cytokines, such as TNF-α, IL-1β, and IL-6, produced in severe COVID-19 can reach ocular tissues via the bloodstream, exacerbating local inflammation." (PMID 39861857, 2025). "Our results are consistent with previous studies and further confirm that in patients with severe COVID-19, decreased lung function is associated with elevated systemic levels of IFN-γ and TNF-α." (PMID 39967737, 2025). "The TNF/TNF receptor 1 (TNFR1) axis has also been associated with mortality; high TNF receptor (TNFR1 and TNFR2) soluble levels are found in COVID-19 patients, although only TNFR1 is related to severity and mortality." (PMID 39940907, 2025). "Compared to healthy individuals, COVID-19 patients have higher levels of inflammatory cytokines, such as interleukin-6 (IL-6), IL-10, and tumor necrosis factor-α (TNF-α)." (PMID 40084335, 2025). "Among others, we investigated the concentration of IL-2 and TNF – cytokines which are some of the best-studied components of the cellular response after vaccination against COVID-19." (PMID 40226625, 2025). "Regarding pro-inflammatory cytokines, we found a reduced expression of TNF-α in the dermis of the COVID-19 group compared to HC." (PMID 40649826, 2025). "Cytokine concentrations (IFN-γ, IL-1Ra, IL-4, IL-6, IL-9, IL-13, and TNF-α) were higher in the breast milk from the breastfeeding mothers with symptomatic and asymptomatic COVID-19 compared with the control group at both sampling times." (PMID 40141241, 2025). "When comparing the serum concentrations of TNF-α and IL-10 between HCs and patients, it was found that patients with moderate and severe ARDS caused by COVID-19 had significantly higher levels of IL-10 (P < 0.001)." (PMID 40761632, 2025). "At low exposure levels, COVID-19-positive individuals maintained consistent production of TNF, IL-2, IL-10, and IL-6, with multiple IFN-γ peaks." (PMID 40406109, 2025). "Serum from patients with severe COVID-19 induced increased levels of IL-1α, IL-1Ra, IL-5, IL-6, IL-10, IL-12(p40), IL-18, IL-27, and TNF-α." (PMID 41583455, 2025). "There was increased transcription of TBK1 and a reduction in transcription of TNFα by RT-qPCR in the COVID-19 group." (PMID 40649826, 2025). "In the first phase of the study, participants in the acute phase of COVID-19 presented patterns of elevated inflammation in the form of high concentrations of cytokines such as TNF (TNF–α), LTA (TNF–β), IL–1β, IL–4, IL–6, IL–8, IL–13, and interferon (IFN) –α2." (PMID 40217938, 2025). "Clinical studies have identified elevated concentrations of pro-inflammatory factors, particularly TNF-α and IL-6, in the serum of COVID-19 patients." (PMID 39962185, 2025). "Critical COVID-19 cases showed higher levels of inflammatory markers (Bilirubin, D-dimer, PCR, and urea, as well as IL-8, IL-10, TNF-α, INF-α, IL-1β, IL-17A, IL-23, IL-6) than moderate and severe groups." (PMID 39861879, 2025).
COVID-19 (continued). "Elevated levels of pro-inflammatory cytokines, such as interleukin-6 (IL-6) and tumor necrosis factor-alpha (TNF-α), have been associated with severe COVID-19 outcomes." (PMID 40002822, 2025). "Unexpectedly, given its pro-inflammatory effects, TNF gene expression was lower in severe/critical COVID-19." (PMID 40532694, 2025). "Our review highlights the importance of taking a history of vaccinations, especially COVID-19 vaccines, and immunosuppressive drugs such as fingolimod, TNF-a inhibitors, and MTX in patients with a recent onset CTCL as a possible cause of disease." (PMID 40226161, 2025). "Elevated plasma Gal-9 levels in COVID-19 patients, for instance, correlate with increased TNF-α and IL-6 expression in monocytes stimulated with rGal-9." (PMID 39951917, 2025). "Taking our results together, we proposed a model to explain that the pathophysiology of critical COVID-19 can be mediated by different pathways, depending on the TNF/IFN-γ levels." (PMID 39940907, 2025). "This disruption contributes to the hyperinflammatory response seen in severe COVID-19 cases, which is marked by elevated levels of cytokines such as IL-6, TNF, and IL-1β." (PMID 40431622, 2025). "Cytokine storm syndrome, characterized by the excessive production of pro-inflammatory cytokines such as IL-6, IL-8, and TNF-α, has been proposed as a key driver of inflammation in the pathogenesis of severe COVID-19." (PMID 40507498, 2025). "Elevated levels of proinflammatory cytokines, such as IL-6, IL-8, and TNF-α, have been identified, reflecting local inflammation and its possible connection to the systemic inflammatory state of COVID-19 patients." (PMID 39859366, 2025). "Biological therapies, such as TNF inhibitors, IL-6 inhibitors, and other targeted agents, are known to interfere with the dysregulated immune signaling that often occurs in severe COVID-19 and related complications." (PMID 40755909, 2025). "A recent publication from the RisCoin study demonstrated impaired humoral responses to COVID-19 mRNA vaccination in patients with IBD receiving immunosuppressive therapies targeting tumor necrosis factor-alpha compared to other commonly used biologics for IBD." (PMID 40863250, 2025). "Higher levels of most soluble mediators were observed in the COVID-19 group than in the healthy control group, with major increases in the levels of proinflammatory cytokines, including IL-6, TNF-α and IFN-γ." (PMID 40608806, 2025). "One important possible mechanism is the cytokine storm and abnormally high levels of inflammatory mediators, such as C-reactive protein, tumor necrosis factor-alpha, and IL-6, seen in COVID-19 patients." (PMID 41002604, 2025). "In COVID-19, the systemic inflammatory response can escalate into a cytokine storm, including IL-1, IL-2, IL-6, TNF-α, IFN-γ, IP-10, GM-CSF, MCP-1, and IL-10—some of which correlate strongly with disease severity." (PMID 40806851, 2025). "Persistent high levels of early response proinflammatory cytokines, including IL-6, TNF-α, and IL-1β, can trigger a cytokine storm in COVID-19 patients." (PMID 40571942, 2025). "In the context of the COVID-19 pandemic, the urgent need to control inflammatory damage has led to early studies exploring the potential of TNF-α inhibitors to reduce disease severity in COVID-19." (PMID 40481519, 2025). "We evaluated a functional profile based on the cytokine production and systemic soluble molecules of COVID-19 patients classified based on TNF/IFN-γ levels." (PMID 39940907, 2025). "Cystatin C also influences the release of key inflammatory mediators such as TNF-α, IL-12, IL-10, and nitric oxide, contributing to inflammation and potential multi-organ failure in severe COVID-19 cases." (PMID 40649865, 2025). "In COVID-19, severe outcomes have increased levels of pro-inflammatory and anti-inflammatory cytokines and chemokines, such as IL-6, TNF-α, IL-10, CCL2, CCL3, CXCL8, and CXCL10, among others." (PMID 40881695, 2025).